DNMT1 (DNA methyltransferase 1)
Diseases named in the same sentence as DNMT1 in open-access papers (continued):
Sharing a sentence is not in itself a finding about the gene and the disease.
Obesity (continued). "Next, we verified which DNMTs among the three isoforms in mammals, DNMT1, DNMT3a and DNMT3b, were responsible for the obesity-induced R2 hypermethylation." (PMID 26139044, 2015). "Suppressing DNMT1 activity with a DNMT inhibitor resulted in the amelioration of obesity-induced glucose intolerance and insulin resistance in an adiponectin-dependent manner." (PMID 26139044, 2015). "Further, we have also shown that DNMT1/3A-mediated methylation at Esr1 promoter played an important role in regulating adipose inflammation, which may contribute to obesity-induced insulin resistance." (PMID 41596507, 2026). "Notably, DNMT1 and DNMT3A, highly expressed in individuals with obesity, contribute to the induction of obesity-associated inflammatory responses." (PMID 40620794, 2025). "Remarkably, individuals with obesity often exhibit heightened levels of DNMT1 expression." (PMID 38068717, 2023). "As a result, it was proposed that the pharmacological suppression of DNMT1 might be considered a viable therapy for obesity and diabetes in which DNMTs are upregulated." (PMID 35163268, 2022). "For example, NFAT5 can regulate thermogenesis and obesity by recruiting DNMT1 to the promoter of b3-adrenoceptor, a key regulator in thermogenesis and obesity, resulting in the suppression of thermogenesis and the beiging of white adipose tissue, leading to obesity and insulin resistance." (PMID 34064510, 2021). "In addition, we also discovered that brown fat Dnmt1 or 3a is important in cold-induced thermogenesis and diet-induced obesity in mice." (PMID 34439754, 2021). "This is consistent with Kim’s report that DNA hypermethylation of a particular region of the adiponectin promoter suppressed adiponectin expression through epigenetic control mediated by a higher DNMT1 expression and, in turn, exacerbated metabolic complications in obesity." (PMID 32586265, 2020). "Interestingly, obesity-induced proinflammatory cytokines triggered expression of DNMT1 and methylation of adipokine gene, whereas treatment with the DNMT inhibitor reverted the process in adipocytes." (PMID 30200265, 2018). "In addition, we demonstrated that the mRNA and protein levels of DNMT1 were dramatically induced by the obesity-related factor LPS or by saturated free fatty acid." (PMID 27530451, 2016). "Obesity-induced, pro-inflammatory cytokines promote DNMT1 expression and its enzymatic activity." (PMID 26139044, 2015). "Thus, it is likely that DNMT1 is guided to the R2 by interacting with particular transcription factor(s) whose binding to the R2 would be altered in obesity." (PMID 26139044, 2015). "Consistent with this, our previous work demonstrated that DNMT1/3A-mediated methylation at the Esr1 promoter in adipocytes suppresses estrogen receptor expression, thereby promoting adipose tissue inflammation and contributing to obesity-induced insulin resistance in female mice." (PMID 41596507, 2026). "Overall, we hypothesized that DNMT1, Bsx and NPY might be involved in triggering dysfunctional differentiation of hypothalamic NPCs in FGR rat offspring, which directly led to the increased susceptibility to obesity in adulthood." (PMID 37378669, 2024). "Pharmacological DNMT1 deficiency promotes selective macrophage activation by blocking PPAR promoter DNA methylation, and DNMT1-deficient mice show improved M2 differentiation, reduced macrophage inflammation, and ameliorated obesity-induced inflammation and IR." (PMID 37020540, 2023). "Over-expression of Dnmt1 in 3T3-L1 adipocytes increases methylation and decreases expression of Adipoq, while its knockdown results in the reverse, suggesting that direct hypermethylation and heterochromatin formation by DNMT1 at the Adipoq gene promoter is involved in obesity pathogenesis." (PMID 33193730, 2020).
Obesity (continued). "In addition, the expression of DNMTs (DNMT1, DNMT3a and DNMT3b) was quantified because they encoded the main enzymes involved in the methylation of DNA and previously we have detected a regulation of these genes after following a VLCKD in blood leukocytes of patients with obesity." (PMID 40140215, 2025). "The decreased trend in the expression levels of HDACs, DNMT1 and DNMT3b is consistent with lowering of the cytosine methylation status in both the promoter and CGI in the obesity group." (PMID 36045397, 2022). "In a diet-induced obesity (DIO) mouse model, Dnmt1 and Dnmt3a mRNA expression was elevated in adipose tissue, especially in epididymal and mesenteric WAT." (PMID 29091029, 2017). "Moreover, we found that DNMT1, DNMT3A and DNMT3B in brown fat are critical for regulating thermogenesis and diet-induced obesity in mice." (PMID 41596507, 2026). "Our study provides strong evidence demonstrating a negative contribution of Dnmt1 to the chemotactic migration of macrophages, in particular in an obesity/LPS-primed pro-inflammatory status." (PMID 37291182, 2023). "On the contrary a clear increase of Dnmt1 was seen with the catechin in the colons of HFD animals while obesity itself had no impact on the transcriptional activity of both genes in colonocytes." (PMID 28133504, 2017).
schizophrenia (38 papers, 2009 to 2026). A major psychotic disorder characterized by abnormalities in the perception or expression of reality. "The study found that the TT genotype and T allele in DNMT1 rs2114724 and the AA genotype and A allele in DNMT1 rs2228611 were associated with schizophrenia." (PMID 37833704, 2023). "DNMT1 overexpression is one of the common features associated with schizophrenia, bipolar and epilepsy disorders." (PMID 38125006, 2023). "A recent study showed the association of minor alleles of rs2228611 (T allele) and rs2114724 (T allele) of DNMT1 with schizophrenia (SZ) and suggested their effects on splicing of the transcripts." (PMID 33854407, 2021). "Though many SNPs reside inside non-coding regions, at least one of them (rs2228611, within DNMT1 exon) has been found to be significantly associated with schizophrenia at genotypic and allelic levels in a South Indian population." (PMID 30687383, 2018). "The genetic variants in DNMT1, rs2114724 and rs2228611, were found to be significantly associated with schizophrenia while de novo DNMTs variants, DNMT3B rs2424932, DNMT3B rs156968, and DNMT3L rs2070565, were associated with early age onset of disease." (PMID 27314012, 2016). "Observations from association analyses of SNPs in DNMT1, DNMT3A, DNMT3B, and DNMT3L indicated that DNMT1 rs2114724 and rs2228611 were strongly associated with schizophrenia at allelic and genotypic level." (PMID 24859147, 2014). "In the present study we report that the polymorphisms in the DNMT1, rs2114724 and rs2228611 are significantly associated with schizophrenia in Malayalam speaking south Indian population." (PMID 24859147, 2014). "In the present study the DNMT1 rs2114724 TT genotype and T allele and DNMT1 rs2228611 AA genotype and A allele were observed to be significantly associated with schizophrenia." (PMID 24859147, 2014). "DNA methyltransferase-dependent DNA methylation in developing interneurons seems to be implicated in schizophrenia, as prenatal stress in mice elevates Dnmt1 and Dnmt3a expression in GABAergic interneurons and induces behaviors indicative of a schizophrenia-like phenotype in their offspring." (PMID 33041771, 2020). "For example, rs2114724 (not present in the expanded PGC dataset) and rs2228611 SNPs in the DNA methyltransferase 1 gene, DNMT1, increase the risk of developing schizophrenia in males or are associated with early onset of schizophrenia and with family history in South Indian population." (PMID 31784692, 2019). "Importantly, the prefrontal cortex GABAergic interneurons of schizophrenia patients express an increase in DNMT1 and 3a, and an increase in TET1 associated with deficits in GABAergic function." (PMID 30564095, 2018). "In addition to the reports that related overexpression of DNMT1 in brain samples from schizophrenia patients, certain alleles of Dnmt1, Dnmt3A, and Dnmt3L have been found to be associated with schizophrenia." (PMID 26798355, 2016). "DNMT1 rs2114724 (genotype P = .004, allele P = 0.022) and rs2228611 (genotype P = 0.004, allele P = 0.022) were found to be significantly associated at genotypic and allelic level with Schizophrenia in South Indian population." (PMID 24859147, 2014). "Similarly, DNMT1 rs2228611 which is a synonymous SNP found in exon 17 and was found to be associated with schizophrenia in our study, has a possible splice regulatory function with G/A resulting in loss of three Exonic splicing enhancer binding motif." (PMID 24859147, 2014). "Association analysis of DNMT1 polymorphisms in schizophrenia." (PMID 24859147, 2014). "Together, DNMT1 overexpression and the resulting gene silencing contribute to GABAergic dysfunction and neural circuit disruptions in schizophrenia." (PMID 39678047, 2024). "In line with study from population with shared ethical background, indicated that the genotype frequency and allelic frequency of DNMT1 rs2114724 and rs2228611 were also correlated with schizophrenia." (PMID 37833704, 2023).
schizophrenia (continued). "The reduction of reelin and GAD-67 in the prefrontal neurons of schizophrenia brains seems to be the consequence of the epigenetic hypermethylation of their promoters by the overexpression of DNA-methyltransferase 1 (DNMT1)." (PMID 38137152, 2023). "Data on schizophrenia (SZ), epilepsy (EPD) and bipolar disorders (BPD) suggested an association of DNMT1 overexpression whereas certain variants of the gene were predicted to result in its increased expression in autism spectrum disorder (ASD)." (PMID 38125006, 2023). "Recent case–control studies indicated a significant association between minor alleles of DNMT1 (rs2114724 and rs2228611), DNMT3B (rs2424932 and rs1569686) and susceptibility of schizophrenia, while it is rare." (PMID 37833704, 2023). "This study investigated the genotype and allele distribution of DNMT1 (rs2114724 and rs2228611) and DNMT3B (rs1569686, rs2424908, rs2424932, and rs6119954) in 134 patients with schizophrenia and 64 healthy controls." (PMID 37833704, 2023). "Decreased levels of SIRT1 in plasma has been linked with a higher comorbidity of depressive symptoms, whereas increased levels of DNMT1 had been observed in the brains of schizophrenia and bipolar patients." (PMID 36768211, 2023). "This is the first report linking rs2114724 and rs2228611 in DNMT1 with positive symptoms of schizophrenia." (PMID 37833704, 2023). "Clozapine, but not haloperidol or risperidone, corrects behavioural phenotypes and normalized the DNMT1 level and 5-mC promoter hypermethylation of schizophrenia-related genes (GAD1, RELN, BDNF) in the PRS animal models." (PMID 36979236, 2023). "As for studies investigating the role of DNMT1 in psychopathology, a postmortem design with individuals with schizophrenia and bipolar disorder reported increased DNMT1 expression and enzymatic activity patients’ brains, compared to controls." (PMID 36440389, 2022). "Some of the genes with differential methylation were previously reported to be associated with schizophrenia, such as AKT1, NOS1, DNMT1, PPP3CC, DTNBP1, and SOX10." (PMID 32764320, 2020). "For instance, elevated levels of DNMT1 were observed in the interneurons of frontal cortex of schizophrenia and bipolar patients with psychosis." (PMID 26798355, 2016). "Recently, a south Indian population was studied for genetic polymorphism in DNMT1, DNMT3A, DNMT3B, and DNMT3L for association with schizophrenia." (PMID 27314012, 2016). "Mechanistically, the relationship between overexpression of DNMT1 and schizophrenia is not fully known although a recent study showed that DNMT1 binds to the promoters of BDNF and GABAergic genes." (PMID 26798355, 2016). "Since DNMT1 cannot by itself establish new DNA methylation marks, it is reasonable to also expect dysregulation of de novo DNMTs in the brain samples with schizophrenia." (PMID 26798355, 2016). "The aim of the present study was to identify the role of genetic variants in DNA MethylTransferases such as maintenance methyltransferase gene (DNMT1) and genes for de novo methyltransferases (DNMT3A & 3B) and DNMT3L in predisposing to schizophrenia." (PMID 24859147, 2014). "Association analysis of DNMT1, DNMT3A, DNMT3B and DNMT3L polymorphisms are summarised by -Log P value for schizophrenia in a South Indian population." (PMID 24859147, 2014). "These include NOS1, AKT1, DTNBP1, DNMT1, PPP3CC and SOX10, which have previously been associated with schizophrenia." (PMID 24399042, 2014). "We screened for polymorphisms in DNA methyltransferases, DNMT1, DNMT3A, DNMT3B and DNMT3L in 330 schizophrenia patients and 302 healthy controls for association with Schizophrenia in south Indian population." (PMID 24859147, 2014). "Our model is also supported by the recently observed overexpression of DNA-methyltransferase 1 (DNMT1) in GABAergic interneurons of schizophrenic brains, apparently actively hypermethylating genes with roles in schizophrenia." (PMID 23391219, 2013).
schizophrenia (continued). "The overexpression of DNMT1 was considered to be one of the etiological factors of schizophrenia." (PMID 38203806, 2024). "Additionally, methionine (MET) treatment, which raises S-adenosyl methionine (SAM) levels, a cofactor for DNMT1, further enhances promoter methylation and gene silencing in schizophrenia-related pathways." (PMID 39678047, 2024). "A two-fold reduction in both GAD-67 and reelin mRNA in GABAergic interneurons isolated from layer I of the cerebral cortex of patients with schizophrenia could be the result of a three-fold increase in DNMT1 activity." (PMID 38137152, 2023). "DNMT1 gene may affect the clinical symptoms of schizophrenia by regulating the expression of genes involved in the dopaminergic and GABAergic systems." (PMID 37833704, 2023). "The observed changes in DNA methylation signatures in schizophrenia were hypothesized to be mediated by increased expression of DNMT1, as elevated DNMT1 mRNA levels were found in post mortem schizophrenic brains." (PMID 33041771, 2020). "For example, polymorphisms in three DNMTs with methylation activity (DNMT1, DNMT3A, and DNMT3B) and in one DNMT without methylation activity (DNMT3L) are associated with an increased risk of schizophrenia." (PMID 30687383, 2018). "In addition, an increased mRNA expression of DNA methyl-transferases (DNMT1 and DNMT3a) has been observed in schizophrenia." (PMID 25206360, 2014). "More specifically, keeping in mind that smoking is frequently abused by schizophrenia patients, nicotine (injected sub-cutaneously) was recently found to decrease DNA methyltransferase 1 expression and glutamic acid decarboxylase 67 promoter methylation in the mouse frontal cortex." (PMID 19956754, 2009). "Elevated DNMT1 levels have also been observed in Brodmann Area 9 (BA9), a region crucial for cognitive functions commonly affected in schizophrenia." (PMID 39678047, 2024). "Previous studies from our research group have described increased DNMT1 mRNA and decreased GAD67 mRNA in the brains of patients with schizophrenia, and our research also shows increased DNMT1 mRNA in the patients’ lymphocytes." (PMID 37056402, 2023). "We examined the haplotype distribution of DNMT1 (rs2114724 and rs2228611) and DNMT3B (rs1569686, rs2424908, rs2424932, and rs6119954) in both the schizophrenia and control groups." (PMID 37833704, 2023). "•Since DNMT1 overexpression is one of the etiological factors for schizophrenia (SZ), the RRBS data generated helps in studying the epigenetic basis of DNMT1 overexpression in abnormal neurogenesis." (PMID 32944600, 2020). "We also found DNMT1, NOS1 and SOX10 to be differentially methylated in brain tissue from patients with schizophrenia." (PMID 24399042, 2014). "While there is an ESC model to investigate the role of DNMT1 overexpression in abnormal neurogenesis, the Dnmt1tet/tet neurons do not have elevated levels of DNMT1 in neurons and therefore do not represent the neurons of schizophrenia patients with psychosis." (PMID 26798355, 2016).